TNF (tumor necrosis factor)
Diseases named in the same sentence as TNF in open-access papers (continued):
Sharing a sentence is not in itself a finding about the gene and the disease.
pancreatic cancer (continued). "In this study, we found both LPS and TNF-α increase COX-2 expression in pancreatic cancer cells, which suggests inflammatory microenvironment may be responsible for the overexpression of COX-2 in some pancreatic cancers." (PMID 21760774, 2011). "EVs derived from pancreatic cancer cell lines incubated with non-polarized macrophages (THP-1 cells) caused higher expression of surface proteins CD14, CD163, and CD206, as well as higher secretion of pro-tumorigenic factors like VEGF, MCP-1, IL-6, IL-1β, MMP-9, and TNF-α." (PMID 35501802, 2022). "However, few serum markers of chronic inflammation have been investigated in relation to CP and pancreatic cancer diagnosis (mainly CRP and cytokines such as Interleukin-6 (IL-6) and Tumour Necrosis Factors (TNF-α)), partially because CP may elevate pancreatic enzymes instead." (PMID 31464604, 2019). "This indicates that in NACT-treated ovarian cancer, TNF/IL6 drives the iCAF phenotype rather than IL1B, which has a leading role in promoting the iCAF phenotype in pancreatic cancer." (PMID 35196078, 2022). "The results showed that TNF-α and anti-TNF-α therapy provided no clinical benefit in terms of the duration of survival of patients with unresectable pancreatic cancer." (PMID 35493517, 2022). "While FADD has recently been reported to have a protective role against anticancer drug-induced cell death in pancreatic cancer cells 9, there are no reports on the effect of FADD knockdown on cell death in OS induced by death ligands such as TNFα or TRAIL." (PMID 32194778, 2020). "There are also some clinical reports of resectable pancreatic cancer patients, which noted low levels of the described pro-inflammatory cytokines (IL-6, IL-1β, IFN-γ, and TNF-α), with their concentrations not correlated with CC, even if more sensitive methods were used for the analyses." (PMID 33557173, 2021). "Our results show that P2X7R (~20-fold), its key inflammasome components: caspase-1 (15-fold), IL-1β (~45-fold), and in addition to (data not shown) IL-18 (~35-fold), IL-33 (~93 folds), TNF-α (~13-fold) and COX-2 (~41-fold) are increased in pancreatic tumors compared to normal pancreas." (PMID 29228654, 2017).
steatosis (307 papers, 2008 to 2026). Increased lipid within the cytoplasm of cells. "Among various cytokines and chemokines, tumor necrosis factor-alpha (TNF-α) and interleukin-6 (IL-6) are recognized as crucial mediators associated with hepatic inflammation and steatosis." (PMID 40863135, 2025). "A growing body of evidence supports the crucial role of TNF-α and other inflammatory cytokines in the progression of pure steatosis to metabolic dysfunction-associated steatohepatitis (MASH)." (PMID 40564877, 2025). "HBx-induced NF-κB activation was associated with the induction of steatosis and apoptosis through promotion of TNF-α production, which is determined by a TNFR1-dependent pathway." (PMID 39091506, 2024). "Derived from macrophage p38α-deficient mice, the primary hepatocytes showed decreased steatosis and inflammatory damage through reduced secretion of pro-inflammatory cytokines (TNF-α, CXCL10, and IL-6), which regulate M1 macrophage polarization." (PMID 36984693, 2023). "Several signaling pathways linked to inflammation, steatosis, and oncogenes can be activated by IL-6 and TNF-α in hepatocytes." (PMID 38313077, 2023). "In the univariate analyses, it was observed that increasing IL-6 and TNF-α levels were significantly associated with liver enzymes according to the three groups, with increasing levels of melatonin, and with steatosis and fibrosis." (PMID 34221262, 2021). "Conclusively, elevated FFA, originating from nutritional overload or released from adipose tissue during fasting, would be the primary cause of TNF release from Kupffer cells that leads to hepatocyte steatosis." (PMID 33050035, 2020). "LCN2 is a downstream TNF inflammatory molecule associated with hepatic steatosis and insulin insensitivity." (PMID 31892368, 2019). "TNF receptor 1 (TNFR1) KO mice are resistant to alcohol-induced liver injury and steatosis, underlying the critical role of TNF-α in the pathogenesis of ALD." (PMID 26769846, 2016). "TNFα is an inflammatory cytokine that plays a major role in the progression from steatosis to NASH, and causes secretion of various other cytokines and chemokines." (PMID 26506376, 2015). "Feeding alcohol to MCP-1–deficient mice results in less steatosis, lower expression of pro-inflammatory cytokines (i.e., of TNFα, IL-1β, and IL-6), and lower levels of oxidative stress than in wild-type mice." (PMID 26695748, 2015). "In murine models of high-fat diet induced steatosis, increased NF-κB activity is associated with elevated hepatic expression of inflammatory cytokines such as TNF-α and activation of Kupffer cells." (PMID 26221176, 2015). "Histological features were confirmed by real‐time PCR analyses, showing alcohol‐induced upregulation of the chemokines MCP‐1/CCL‐2 and CXCL1, along with the cytokine TNF‐α, implicated in hepatic inflammation, and of PPARγ that promotes both hepatic inflammation and steatosis." (PMID 39921321, 2025). "Like IL-6 and TNFα, IL-1 is commonly induced in steatotic livers when macrophage proliferation and infiltration are induced and is necessary for the whole spectrum of pathologies associated with steatosis, injury and cancer." (PMID 36276076, 2022). "In addition, OA-induced steatosis causes changes in cell morphology; increases tumor necrosis factor alpha (TNF-α) levels, lipid peroxidation, and apoptosis; and decreases expression of peroxisome proliferator-activated receptor alpha (PPAR-α)." (PMID 36012291, 2022). "Results showed that miR-124-3p overexpression increased triglyceride levels and TNFα expression, suggesting that miR-124-3p may have a causal effect on steatosis in the liver." (PMID 33324345, 2020). "Steatosis is associated with increased levels of ROS and the induction of low level inflammatory response including the release of proinflammatory cytokines such TNFα." (PMID 21760938, 2011).
steatosis (continued). "Thus, we assessed serum levels of neuron-specific enolase (NSE), transglutaminase 2 (TGM2), and glial fibrillary acidic protein (GFAP) as indirect markers of BBB dysfunction and examined their associations with steatosis severity, TNF-α and IL-10 in patients with morbid obesity." (PMID 42195075, 2026). "From weeks 8 to 13, disease progressed in FFC-fed animals from simple steatosis with slight signs of inflammation to macrovesicular steatosis with an increase in the number of inflammatory foci also associated with elevated levels of proinflammatory cytokines like TNFα and IL6." (PMID 32235497, 2020). "Their results indicated that the adipocyte module significantly affected NAFLD’s progression in hepatocytes, evidenced by insulin-resistant biomarkers, differential adipokine signaling, and increased tumor necrosis factor-alpha (TNF-α)-induced steatosis." (PMID 41304443, 2025). "CD47 deficiency enhances NF-κB activation, elevates IL-1β, TNFα, IL-6, reduces IL-10, increases CCL2 and macrophage infiltration, leading to exacerbated steatosis, inflammation, and fibrosis." (PMID 40630093, 2025). "In a recently published preclinical report, chronic supplementation with BHB salts, like that used in the current study, preserved hepatic structure, reduced inflammatory cytokines (e.g., TNF-α), and minimized steatosis." (PMID 41305632, 2025). "In particular, the presence of macrovesicular steatosis and vascular congestion in the KE and BD groups further supports the inflammatory and metabolic stress findings seen in TNF-α and arginase staining." (PMID 41155552, 2025). "Pharmacological and genetic inhibition of nSMase2 prevented intracellular lipid accumulation and TNFα-induced inflammation in in-vitro HepG2-steatosis cellular model." (PMID 38474427, 2024). "It has been reported that inflammatory cytokines such as TNFα increase during the progression from simple steatosis to fibrosis in NAFLD." (PMID 39336763, 2024). "Enhance the expression of ZO-1, Claudin-1 and Occludin, decrease the expression of LPS, TNF-α, IL-6 and IL-1β, enhance intestinal barrier, and reduce inflammatory response, hepatocyte steatosis and collagen fiber deposition." (PMID 39234554, 2024). "Patients with steatohepatitis had greater blood TNF-α levels than healthy individuals with simple steatosis." (PMID 38751599, 2024). "Oxidative stress/damage, mTOR activation, and/or TNFα levels induced by steatosis or aging in liver triggers necroptosis in liver cells." (PMID 39514172, 2024). "TNF and IL-1β are key cytokines in MASLD, driving the development of steatosis, inflammation and fibrosis, and the majority TNF and IL-1β molecules in the liver are derived from activated macrophages." (PMID 39372417, 2024). "Notably, even at this moderate level of suppression, the nSMase2 deficiency caused a significant reduction in TNF-α transcripts and protein expression in HepG2 cells under steatosis-inducing conditions, implying that nSMase2 had a potential role in inducing inflammation in this model of steatosis." (PMID 38474427, 2024). "Adiponectin protects the liver from steatosis and inflammation by directly suppressing TNF-α and decreases the concentration of free fatty acids." (PMID 38732625, 2024). "Steatosis is reported to lead to increased signaling of the transcription factor NF-κB, which can induce the production of pro-inflammatory mediators, such as TNF-α, IL-6 and IL-1β27." (PMID 37468618, 2023). "Pathways driven by macrophages include not only fibrosis and inflammation but also steatosis via secretion of tumor necrosis factor alpha (TNF-α), IL-1β, CC-chemokine ligand 2, and monocyte chemoattractant protein-1 (MCP-1)." (PMID 39872860, 2023). "In fact, CeNPs have been demonstrated to decrease total saturated fatty acids and foam cell production (steatosis), reactive oxygen species production and TNF-α (necrosis), and vacuolization in hepatic tissue when used to treat NAFLD." (PMID 37958712, 2023).
steatosis (continued). "On the other hand, elevated TNF-α can lead to hepatic TG accumulation and steatosis, which in turn activates NF-κB, thus form a vicious cycle of aggravating liver damage." (PMID 37533076, 2023). "Amplifying the expression of TRIM59 further exacerbated steatosis and substantially heightened the secretion of TNF-α, IL-6 and IL-8." (PMID 37867509, 2023). "The current study confirms its potent antioxidant, anti-inflammatory and anti-steatosis activities through the suppression of TNF α, arginase and PPAR α induced by CCl4." (PMID 36717906, 2023). "In agreement with in vitro findings, NaBu significantly reduced hepatic TNF-α protein expression and proinflammatory gene expressions along with concomitant reduction in steatosis and infiltrations of inflammatory cells in the liver parenchyma." (PMID 37202387, 2023). "In a study of male rats, an 8-week exposure to 20% Fru (w/v) in drinking water led to significant increases in the expression of IL-6 and TNF-α in the liver, which was accompanied by obvious steatosis and pathological features of inflammation." (PMID 35495917, 2022). "One of the proinflammatory cytokines produced with steatosis, TNFα, plays a key role in liver carcinogenesis." (PMID 36276076, 2022). "Binge drinking of ethanol led to weight loss in the body and spleen, liver inflammation and steatosis, and increased serum ALT and AST levels (markers of liver injury), along with increased IL-1β, TNF-α, and iNOS expression levels in mice." (PMID 35165521, 2022). "Afterwards, an in vivo study showed that inhaled PM2.5 pollutants induces steatosis and portal inflammation with increasing expression of inflammatory factors such as IL-6, TNF-α, NF-κB in the liver." (PMID 36011940, 2022). "Compared to untreated hepatocytes in healthy medium, steatosis increased in both healthy and diabetic medium for TNF-α treated cells." (PMID 34162924, 2021). "There was also an increase of mRNA levels of inflammatory pathway genes toll-like receptor 9 (Tlr9) and tumor necrosis factor (Tnf-α) with steatosis." (PMID 34257827, 2021). "Circulating TNF levels have been reported to be higher in patients with NASH than in patients with steatosis and control individuals." (PMID 34447378, 2021). "Statins have been demonstrated to decrease hepatic FFA, steatosis, hepatic fibrosis, and the expression of inflammatory markers TNF-α and IL-6." (PMID 34444990, 2021). "Pentoxifylline is a methylxanthine by-product that has been demonstrated to improve ALT levels, as well as steatosis, inflammation, and fibrosis inhibition TNF-α." (PMID 34444990, 2021). "NFKBIA overexpression is related to steatosis development by induction of hepatocyte apoptosis and secretion of TNF-α and IL-1β by Kupffer cells." (PMID 33785040, 2021). "The translocation of microbial endotoxins, such as lipopolysaccharides, have been shown to induce steatosis, inflammation, and fibrosis, as well as elevated inflammatory cytokines, such as TNF-alpha (TNF-α)." (PMID 34579068, 2021). "This carotenoid suppressed proinflammatory cytokines secretion (TNF-α and IL-6) reversing inflammation, steatosis, and fibrosis progression in NASH by repressed macrophage activation." (PMID 33628797, 2021). "In this study, we used the human hepatocyte cell line HepG2 as a model for NASH and treated these cells with FFA to induce steatosis, followed by treatment with TNFα to mimic the inflammatory processes within the liver." (PMID 34440652, 2021). "In this regard, active macrophages increase the secretion of inflammatory cytokines, such as TNF-α and IL-6, which can further aggravate hepatocyte steatosis." (PMID 32326594, 2020). "Other studies have reported that ATM regulates atopic dermatitis-like lesions, and its active flavonoids have been shown to suppress a TNF-α–related pathway in ethanol-induced liver injury and steatosis in mice." (PMID 33029297, 2020).
steatosis (continued). "Despite these differences, our data indicate that the LPS-induced steatosis also depends on Kupffer cell-derived TNF." (PMID 33050035, 2020). "FFC-fed mice progressed from simple steatosis to early non-alcoholic steatohepatitis, along with significantly higher TNFα and IL-6 protein levels in the liver and impaired glucose tolerance." (PMID 32235497, 2020). "The steatosis was also accompanied by an increase in the expression of pro-inflammatory interleukins (IL), IL-1β and TNF in PCLS." (PMID 32094147, 2020). "We also observed dose-dependent steatosis, which in turn lead to dose-dependent upregulation of the inflammatory marker TNFα." (PMID 31940797, 2020). "Portal macrophages are detectable in steatosis alone as the earliest change, followed by an elevated expression of pro-inflammatory cytokines such as IL-1α and TNF-alpha in early NASH." (PMID 33202693, 2020). "miR-34a expression in HFD-fed mice was positively correlated with liver cholesterol level (r2 = 0.98), TNF-α (r2 = 0.69), and steatosis (r2 = 0.66)." (PMID 31885789, 2019). "Further, deletion of TNF in experimental mouse models of NAFLD correlates with decreased steatosis, fibrosis and improved glucose tolerance." (PMID 31921154, 2019). "Treatment with anti-TNF antibody and metformin, an antidiabetic drug that inhibits hepatic TNF-α expression, was found to improve steatosis in ob/ob mice." (PMID 31438528, 2019). "Macrophage produced cytokines (e.g., IL-6, TNF, IL-1β) can directly target hepatocytes and promote steatosis, inflammation and hepatocellular damage." (PMID 31921154, 2019). "TNF-alpha, an inflammatory cytokine modulating MMPs involved in repair and remodeling, plays a major role in the progression from steatosis to NASH." (PMID 30854350, 2019). "The administration of TNFα antibody into ob/ob mice induces steatosis improvement, supporting a role of TNFα in NAFLD progression." (PMID 29954129, 2018). "AST, ALT, γGT, CRP, TNF-α and IL-6 as well as the histological characteristics (steatosis and fibrosis of the patients) were significantly improved compared with the patients who received the placebo." (PMID 28820468, 2017). "Sensitization of Kupffer cells to gut-derived LPS was shown to contribute to the initiation and progression of NASH; Kupffer cells-derived TNF-α has been identified as an important mediator of steatosis, inflammation, and hepatocyte damage." (PMID 28167852, 2017). "Dose response data shows that maximal effects of glucagon and TNF alpha for reduction or reversal of insulin-induced steatosis are active at >1 μg/ml glucagon and 100 nM TNF alpha, respectively." (PMID 29430572, 2017). "Inflammasome-deficient mice showed a reduction of Firmicutes and an increase of Bacteroidetes, associated with increased steatosis and inflammation via TLR4 and TLR9 activation, leading to enhanced hepatic TNF-transcription." (PMID 27483246, 2016). "Previous studies have reported that eotaxin-2/CCL24, IL-1α, IL-12, and TNF-α, respectively, are the important mediators in the steatosis model." (PMID 25799095, 2015). "Comparably, in our research, omnipresent immunopositivity in the CCl4 group suggested a high levels of TNF-α, accompanied by obvious steatosis and oxidative lesion, which was sustained in CCl4 control group with moderate improvement." (PMID 26295240, 2015). "These processes lead to the production of several pro-inflammatory cytokines (e.g., of TNFα, IL-1β, IL-8, and IL-17), triggering steatosis in hepatocytes and inducing fibrogenic pathways in HSCs." (PMID 26695748, 2015). "In conclusion, the present study showed that a soybean diet prevented steatosis at least in part through reduced lipogenesis but resulted in TNFα-mediated inflammation." (PMID 25892856, 2015). "Since Kupffer cells are the major producers of the cytokines that modulate TNF-α and IL-6 activity, higher TNF-α expression in our prenatal steroid group suggests that steatosis was related to Kupffer cell dysfunction or activation." (PMID 24822223, 2014).